G6PD (glucose-6-phosphate dehydrogenase)
Diseases named in the same sentence as G6PD in open-access papers (continued):
Sharing a sentence is not in itself a finding about the gene and the disease.
G6PD deficiency (continued). "However, primaquine can cause intravascular hemolysis in individuals with G6PD deficiency, which, depending on the G6PD variant, may increase the risk of primaquine-induced hemolysis from mild to severe." (PMID 24853873, 2014). "Thus, G6PD deficiency testing and a G6PD genotyping are required before treatment." (PMID 24853873, 2014). "Additionally, it is possible that unrecognized genetic modifiers of G6PD activity have yet to be identified, and that these may play a role in determining an individual’s G6PD deficiency status." (PMID 25201310, 2014). "Glucose-6-phosphate dehydrogenase (G6PD) is an X-linked recessive hereditary disorder that currently affects 200–400 million people worldwide, with over 160 mutations identified and there is pronounced geographical overlap between areas of G6PD deficiency prevalence and malaria endemicity." (PMID 23782846, 2013). "Erythrocytes with insufficient G6PD are thus unprotected against oxidative injury, and individuals with G6PD deficiency may develop haemolytic anaemia in response to a number of stresses, including infection and exposure to medications such as the 8 amino-quinoline, primaquine." (PMID 23782846, 2013). "This identified another 7 patients who were G6PD deficient according to this test, of whom 1 male was hemizygous for the Mahidol variant and another male showed the relatively common 1311C→T intron 11 nt93T→C mutation, both associated with mild G6PD deficiency." (PMID 23926329, 2013). "Moreover, eryptosis is enhanced in several clinical conditions, such as iron deficiency, sickle-cell anaemia, beta-thalassaemia, glucose-6-phosphate dehydrogenase (G6PD)-deficiency, phosphate depletion, Haemolytic uremic syndrome, sepsis, malaria and Wilson's disease." (PMID 21599958, 2011). "For diabetes there is debate whether HbA1C is superior to fasting blood sugar and glucose tolerance test, because of its relatively high cost and the potential difficulty in its interpretation in the presence of haemoglobinopathies and glucose-6-phosphate dehydrogenase (G6PD) deficiency." (PMID 20482860, 2010). "This study aims to: 1) determine the prevalence of G6PD deficiency in a random sample of healthy Iraqi Kurdish males attending a regional premarital screening center, and 2) define the molecular basis of G6PD deficiency among a sample of G6PD deficient males in the same region." (PMID 20602793, 2010). "Therefore, large doses of methylene blue may result in higher levels of methylene blue than of leucomethylene blue, which will result in hemolysis and, paradoxically, methemoglobinemia in patients with glucose-6-phosphate dehydrogenase (G6PD) deficiency." (PMID 20181170, 2010). "However, in high-prevalence areas of G6PD deficiency, more than 40% of neonates with jaundice that might require exchange transfusion are G6PD-deficient, hence the incidence and severity of these complications are expected to be higher." (PMID 20376264, 2010). "G6PD deficiency may also be assessed by analysis for mutations in the G6PD gene." (PMID 19789650, 2009). "As conflicting conclusions regarding malaria risk and G6PD deficiency may have been due to different detection methods, we characterized G6PD status by both enzymatic and genotypic assays in a cohort of Ugandan children and assessed correlations between the two measures and the risk of malaria." (PMID 19789650, 2009). "The fact that G6PD-deficiency is rare in Germany but relatively common in the Mediterranean region and Northern Africa gave rise to speculations in the past that G6PD-deficiency was spread into German populations, as the Roman Empire had occupied the countries beyond the Alps." (PMID 17637841, 2007). "Of course, spherocyte formation may be a consequence of the pitting of intraerythrocytic inclusion bodies like Howell-Jolly bodies or the Heinz bodies produced in conditions associated with RBC oxidant stress such as glucose-6-phosphate dehydrogenase (G6PD) deficiency." (PMID 16879740, 2006).
G6PD deficiency (continued). "Glucose-6-phosphate dehydrogenase deficiency (G6PDD) being highly prevalent in the Middle East, the primary objective was to estimate the incidence of neonatal jaundice among G6PD-deficient neonates and to explore its association with various risk factors." (PMID 38480787, 2024). "When qualitative testing was selected, experts suggested using PQ14 (low dose) in G6PD normal patients among five out of eight scenarios and PQ8 weekly for G6PD deficiency." (PMID 38776349, 2024). "The G6PD deficiency was categorized as class I, corresponding to the World Health Organization (WHO) classification, due to the drastic decreased G6PD enzyme activity and development of CNSHA." (PMID 39684266, 2024). "Among the 288 males with G6PD variants, 276 with positive biochemical NBS results were directly diagnosed with G6PD deficiency." (PMID 39436963, 2024). "It proposes two proactive measures: screening for the G6PD rs72554664 mutation in those with G6PD deficiency to evaluate their T2DM risk, and regular glucose monitoring for hemizygous males with the G6PD rs72554664-T risk allele." (PMID 38834682, 2024). "In summary, shorter course ascending dose vivax malaria radical cure regimens in G6PD-deficient subjects offer the prospect of an effective treatment which does not incur prohibitive haemolytic toxicity and in some areas could obviate the need to test for G6PD deficiency." (PMID 38319064, 2024). "Glucose-6-phosphate dehydrogenase (G6PD) is a the first and rate-limiting enzyme that plays a critical role in G6PD deficiency, the most common enzyme disorder worldwide, is related to intravascular hemolysis." (PMID 38188142, 2024). "One cross-sectional survey in Papua, Indonesia reported a G6PD deficiency prevalence as determined by the RDT of 21%, which is in stark contrast to other reports from the area that reported local phenotypic G6PD prevalence of 2.6%." (PMID 38687748, 2024). "In this study, 10% of malaria RDT-negative participants had G6PD activity below 30% when considering the site-specific AMM, which is consistent with previous estimates of the prevalence of G6PD deficiency in Cambodia that range from 7 to 13%." (PMID 36986323, 2023). "For instance, despite 64% being heterozygotes for the variant G6PD Med, consistent with the partial phenotype, the remaining 25% did not carry any of the variants screened, suggesting the presence of unknown or missed variants or, less likely, an acquired form of G6PD deficiency." (PMID 36829893, 2023). "Individuals with glucose-6 phosphate dehydrogenase (G6PD) deficiencies can experience hemolysis if they are administered PQ, and many populations in malarious regions have high prevalence of G6PD deficiency." (PMID 36635642, 2023). "The CareStartTM G6PD RDT test showed good sensitivity and specificity when compared with the standard quantitative assay when diagnosing G6PD deficiency." (PMID 37127600, 2023). "G6PD genotyping was performed on all 193 females and 183 males, including all with G6PD deficiency (75 samples) defined by either spectrometry or RDT methods, and 108 G6PD-normal were selected randomly." (PMID 37127600, 2023). "Patients with COVID-19 and G6PD deficiency had lower WBC, ANC, lymphocyte, monocyte, and eosinophil counts compared with COVID-19 patients with normal G6PD." (PMID 36466438, 2022). "All members of this class of drugs can cause haemolysis in individuals with low activity of the Glucose-6-Phosphate Dehydrogenase (G6PD) enzyme, usually referred to as G6PD deficiency." (PMID 36195916, 2022). "However, genotyping of G6PD is essential not only for diagnosis but also for epidemiological investigations and genotype-phenotype correlation studies, which are of great significance for genetic counseling, prognosis prediction, and the management of G6PD deficiency." (PMID 36212124, 2022). "Since G6PD deficiency is very common in malaria-endemic areas, WHO have recommended G6PD testing before giving PQ." (PMID 36384674, 2022).
G6PD deficiency (continued). "Moreover, a 4-day old Panamanian male infant with G6PD deficiency developed severe jaundice and kernicterus only from direct contact with or inhalation of vapor from naphthalene-impregnated clothes, and subsequent genotyping revealed an underlying G6PD Mediterranean variant." (PMID 35685917, 2022). "Outpatients were screened for G6PD deficiency using CareStartTM rapid diagnostic test (RDT) and CareStartTM G6PD biosensor in Nouakchott, Mauritania, in 2019–2020." (PMID 34353361, 2021). "In this study, we aimed to evaluate the performance of a point-of-care, semi-quantitative test for G6PD deficiency, the STANDARD G6PD Test, in a malaria-endemic setting in Brazil." (PMID 34383774, 2021). "To support this hypothesis further, we conducted field surveys for G6PD deficiency (unpublished) in a western Indonesian tribe, the Balinese group of Bali Island, and an eastern Indonesian tribe, the Sasak group of Lombok Island, and compared the distributions of G6PD variants." (PMID 34930507, 2021). "For G6PD testing, WST-8 was applied, in 96-well format, to the screening of G6PD deficiency in different populations." (PMID 33879156, 2021). "The diagnosis of the G6PD deficiency is based on the blood count and smear (CBC), qualitative and quantitative tests of the G6PD activity, or (PCR)." (PMID 33925963, 2021). "At the 30% threshold for G6PD deficiency, the STANDARD G6PD Test demonstrated excellent performance on both capillary and venous specimens, with 100% sensitivity and >97% specificity for both sample types." (PMID 34383774, 2021). "We show that Fyn acts as redox sensor, specifically targeting G6PD to protect GSH and Prx2, which are required to remove peroxides that contribute to hemolysis in individuals with G6PD deficiency." (PMID 32863204, 2020). "Indeed, guidelines for G6PD screening have been shown to prevent the omission or oversight for later testing when oxidant drugs are administered on an urgent or emergent basis and have been linked with reduced risk of complications associated with G6PD deficiency in HIV patients." (PMID 32802082, 2020). "For children with glucose-6-phosphate dehydrogenase deficiency (G6PD), WHO recommended testing G6PD before prescription of anti-malaria drug to ensure safe administration of primaquine for preventing relapse of P. vivax and P. ovale malaria." (PMID 31533756, 2019). "Among the 130,635 newborns (71511 males and 59124 females) screened for G6PD enzyme activity using fluorescent spot-test (FST), a total of 9583 cases (7832 males and 1751 females) were suspected as G6PD deficiency." (PMID 29339739, 2018). "Glucose-6-phosphate dehydrogenase (G6PD) deficiency is typically screened for prior to high dose IVC administration, due to two case reports of hemolytic anemia in G6PD deficient individuals following 80 g IVC administration." (PMID 30190680, 2018). "Since the study only deployed a G6PD deficiency RDT, enzymatic activity validation is ultimately required to evaluated functional loss of G6PD activity to disentangle female heterozygotes from deficient and the non-deficient females." (PMID 29558929, 2018). "Furthermore, G6PD enzyme activity may be elevated in early life and this may mask G6PD deficiency." (PMID 28797255, 2017). "The diagnosis of G6PD deficiency is commonly based on the results of a fluorescent spot test for NADPH generation and a quantitative spectrophotometric assay of G6PD activity." (PMID 28728551, 2017). "Here we report an analysis of multiple allelic forms of G6PD deficiency in a large multi-centre case-control study of severe malaria, using the WHO classification of G6PD mutations to estimate each individual’s level of enzyme activity from their genotype." (PMID 28067620, 2017). "Another study that investigated the relationship between sickle cell disorders and G6PD deficiency in Central-Eastern India recorded a 0.61% prevalence of SCT and G6PD co-inheritance." (PMID 29021902, 2017).
G6PD deficiency (continued). "The CareStartTM G6PD RDT showed 100 % sensitivity and NPV for detecting G6PD deficiency at the cut-off activities of ≤10 and ≤20 % of normal activity compared to the reference enzymatic method." (PMID 27329471, 2016). "For vivax malaria, radical cure with primaquine (0.75 mg/kg weekly for 8 weeks or 0.25 mg/kg daily for 14 days) is recommended only if glucose-6-phosphate dehydrogenase (G6PD) deficiency testing is performed and G6PD deficiency is excluded." (PMID 27708187, 2016). "Genetic analysis of G6PD deficiency was carried out using RFLP and specifically determined common sub-Saharan African G6PD genotypes." (PMID 27456336, 2016). "The most widely used and recommended procedure for screening patients for G6PD deficiency, excluding newborn screening, is the fluorescent spot test (FST), described by G6PD pioneer Ernest Beutler in 1966." (PMID 26894297, 2016). "Oxidant hemolysis caused by its metabolite hydroxylamine is a reported side effect in patients with glucose-6-phosphate dehydrogenase (G6PD) deficiency and therefore screening for G6PD deficiency is recommended before the drug is started." (PMID 25628986, 2015). "Because G6PD deficiency is notoriously common in malaria endemic areas, WHO recommended G6PD testing before giving PQ." (PMID 25915902, 2015). "In this study, we surveyed the prevalence of G6PD deficiency in 1770 subjects of the Kachin ethnicity in the China-Myanmar border area using a fluorescent spot test (FST) and determined the G6PD variants in 198 unrelated G6PD deficient subjects." (PMID 26226515, 2015). "Diagnostic performance of CareStart G6PD RDT by gender compared to Trinity Biotech Quantitative and Qualitative methods for G6PD deficiency screening." (PMID 25885097, 2015). "We might also surmise that variation in hENT1 expression in G6PD deficiency could produce a spectrum of metabolic constraint that could contribute to differential susceptibility to favism and/or drug sensitivity between different individuals with G6PD-deficiency." (PMID 26688730, 2015). "In total, 3.3% of patients had a variant G6PD genotype, which compares to an earlier study in North Sumatera showing a 5% prevalence of G6PD deficiency; the slightly lower prevalence in vivax patients in the current study might relate to the protective effect of G6PD deficiency against malaria." (PMID 23926329, 2013). "The possible association between scleral icterus and G6PD deficiency discovered in this study, if confirmed in larger studies, could be used by those designing screening programs to identify children who are more likely to be G6PD deficient and should be prioritized for screening." (PMID 23874768, 2013). "Moreover, because current drugs for radical cure may cause serious side effects in patients with glucose-6-phosphate dehydrogenase (G6PD) deficiency, more information is needed on the distribution of G6PD-deficiency variants as well as tests to identify at-risk individuals." (PMID 21311583, 2011). "The impact of G6PD deficiency on parasite clearance with ACT treatment was compared between G6PD-deficient patients and G6PD-normal group." (PMID 21092137, 2010). "G6PD genotyping and separate analysis of hemizygous males/homozygous females versus heterozygote females and G6PD-normal patients was necessary to show the clinical importance of the interaction between CDA and G6PD deficiency for hematological safety." (PMID 19690618, 2009). "Mutations in the haemoglobin beta-globin (HbB) and glucose-6-phosphate dehydrogenase (G6PD) genes cause widespread human genetic disorders such as sickle cell diseases and G6PD deficiency." (PMID 16356170, 2005). "Previous case-control studies did not estimate the prevalence of undiagnosed G6PD deficiency in a diverse population like the UK or estimate the impact of G6PD carrier status on delays-in-T2D diagnosis." (PMID 41022122, 2025).
G6PD deficiency (continued). "In the context of G6PD deficiency, we found that in G6PD*B/G6PD*A heterozygotes, gene expression did not appear to vary according to which allele was silenced." (PMID 41286645, 2025). "This is in line with expectations that even those with relatively severe G6PD deficiency are able to tolerate PQ in low doses, suggesting that ‘universal’ PQ was well tolerated regardless of G6PD status or individual variations in body size." (PMID 41382293, 2025). "Glucose-6-phosphate dehydrogenase (G6PD) deficiency presents silently and is not routinely screened." (PMID 41022122, 2025). "To date, a few qualitative tests for G6PD deficiency are available, including the fluorescent spot test as well as some lateral flow rapid diagnostic tests (CareStart G6PD RDT, AccessBio, USA and BinaxNOW G6PD Test, Alere, USA)." (PMID 40597115, 2025). "Overall, despite the strong recommendations of the World Health Organization, screening blood donors for G6PD deficiency is not a common practice, and so blood banks and transfusion services have G6PD-deficient RBCs in their inventories." (PMID 40367898, 2025). "Brazil, like most endemic countries, has been prescribing a 7-day primaquine regimen for radical cure without testing for glucose-6-phosphate-dehydrogenase (G6PD) deficiency to exclude those at risk of primaquine-induced haemolysis." (PMID 40978565, 2025). "Although severe G6PD-deficient patients did not exhibit increased hemolysis or ineffective erythropoiesis in the nonacute phase, the present findings of severe G6PD deficiency revealed increased levels of miR-451a (approximately 6 fmol/μL)." (PMID 38992151, 2024). "The clinical application of G6PD testing is to guide the administration of radical cure, and in this scenario the negative predictive value (NPV) is more relevant than sensitivity or specificity and is dependent on the underlying prevalence of G6PD deficiency." (PMID 38687748, 2024). "Both studies used standard 14-day dose regimens of primaquine, and neither conducted G6PD testing before administration of primaquine, although background rates of G6PD deficiency were considered low." (PMID 38118171, 2024). "G6PD activity in RBCs from neonates without G6PD deficiency is higher than that in adult RBCs; in addition, there is a significantly negative correlation between gestational age and G6PD activity, with peak levels at 29–32 weeks of gestational age." (PMID 39594591, 2024). "Despite the recommendation for G6PD normal individuals, patients were not treated with primaquine because of a relatively high prevalence of G6PD deficiency of 8–19%, a lack of PoC G6PD testing, and concerns about severe hemolysis following drug exposure." (PMID 39028699, 2024). "In the past decade, advances in point-of-care G6PD tests have reinvigorated calls for optimising the dose of primaquine in individuals without G6PD deficiency." (PMID 37748496, 2024). "Our current study did not reveal any pathogenic mutation associated with G6PD deficiency or accumulation of deleterious G6PD variants." (PMID 38674343, 2024). "They found that in men with G6PD deficiency, G6PD activity never reached the normal range, and baseline G6PD activity was unaffected by fever." (PMID 38725027, 2024). "The higher detection of G6PD deficiency in our study were owing to the use of a quantitative G6PD activity assay, the OSMMR-2000D kit assay, rather than the widely used semiquantitative FST." (PMID 38085718, 2023). "Therefore, the aim of this study was to evaluate the prevalence of G6PD deficiency in Korea by analyzing the utilization of G6PD activity tests and results from a large number of patients using the current WHO classifications for G6PD enzyme activity." (PMID 37176619, 2023). "EGRAC is not a suitable test of riboflavin status in people with glucose-6-phosphate dehydrogenase (G6PD) deficiency because GR retains FAD leading to higher GR activity and low EGRAC." (PMID 37988268, 2023).